CCND1 (cyclin D1)
Diseases named in the same sentence as CCND1 in open-access papers (continued):
Sharing a sentence is not in itself a finding about the gene and the disease.
glioma (continued). "Our model analysis revealed an ultrasensitive mechanism of cyclin D1 degradation that controls the glioma differentiation induced by the cAMP inducer cholera toxin (CT)." (PMID 27515956, 2016). "To further explore the possible mechanism by which RACK1 promoted the glioma cell cycle, we then investigated the protein levels of G1/S transition key regulators, such as Cyclin D1 and CDK6." (PMID 27763568, 2016). "Our stochastic modeling of glioma differentiation therapy as a realistic case study demonstrated that increased noise can modulate the ultrasensitivity of cyclin D1 activity and decrease the efficiency of drug-induced glioma differentiation." (PMID 27515956, 2016). "Our analysis indicated that noise can interfere with the ultrasensitive response of cyclin D1 and reduce the differentiation efficiency by inducing heterogeneous responses of glioma cells to drugs." (PMID 27515956, 2016). "Our results demonstrated that targeting the noise-induced dynamics of cyclin D1 during glioma differentiation therapy can increase anti-glioma effects, implying that noise is a considerable factor in assessing and optimizing anti-cancer drug interventions." (PMID 27515956, 2016). "MAGI3 immunoreactivity was downregulated concomitant with upregulation of Cyclin D1 in glioma cells compared with adjacent normal cells." (PMID 26452219, 2015). "Consistently, MAGI3 overexpression in glioma cells C6 suppressed expression of β-catenin target genes including Cyclin D1 and Axin2, whereas MAGI3 knockdown in glioma cells U373 and LN229 enhanced their expression." (PMID 26452219, 2015). "Activation of PI3K/Akt leads to upregulation of cell-cycle regulator Cyclin D1 and downregulation of p27Kip1, resulting in the promotion of glioma proliferation, cell cycle progression and a significant increase in the percentage of S-phase cell." (PMID 25823655, 2015). "Among cell cycle regulators, IDHwt gliomas were significantly more likely to have CDK1 loss and less likely to have cyclin A1 gene loss or cyclin D1 or E2 gene gain." (PMID 26091668, 2015). "Based on these data, we believe that Sch B arrests the cell cycle in G0/G1-phase to suppress the proliferation of glioma cells by reducing the expression of cyclin D1 and CDK4." (PMID 25685066, 2015). "STAT3 knockdown with interfering RNA, delivered by a lentivirus vector, resulted in down-regulation of cyclin D1 and inhibition of glioma cell proliferation." (PMID 24518612, 2014). "Further studies showed that Cyclin D1 was a novel direct target of miR-15b and was frequently downregulated in glioma tissues and cell lines." (PMID 24995320, 2014). "The higher expression of Cyclin D1 was found in glioma tissues compared to the normal brain tissues." (PMID 24995320, 2014). "Recently, suppression of Cyclin D1 reduced the proliferation and invasiveness of glioma cells while inducing apoptosis, suggesting the crucial role of Cyclin D1 in gliogenesis and defining Cyclin D1 as a promising molecular target for anticancer therapy." (PMID 24995320, 2014). "Suppression of PI3K in U251 and U87 glioma cells with LY294002 treatment led to the upregulation of E-cadherin while decreasing Cyclin D1 and p-Rb." (PMID 24650096, 2014). "miR-195 inhibits glioma cell proliferation by downregulating expression of Cyclin D1 and cyclin E1, through directly targeting the 3′-UTR of Cyclin D1 and cyclin E1." (PMID 24995320, 2014). "Overexpression of cyclin D1 has been shown to induce glioma invasion by increasing metalloproteinase activity and cell motility." (PMID 24465715, 2014). "MiR-15b inhibited U87 and LN229 glioma cells growth at least partially by regulating the 3′-untranslated regions (3′-UTR) of Cyclin D1." (PMID 24995320, 2014). "Taken together, our results suggest that miR-195 inhibit glioma proliferation both in vitro and in vivo by repressing Cyclin D1 and Cyclin E1 expression." (PMID 23383003, 2013).
glioma (continued). "We previously showed that knockdown of BRG1 in glioma cell lines resulted in significantly reduced cell proliferative ability, and this reduced cell proliferation is due to G1 phase arrest as cyclin D1 is downregulated." (PMID 23533649, 2013). "MiR-195 levels in 10 freshly collected glioma samples inversely correlated with the expression of Cyclin D1 (r = −0.709, P = 0.022), and Cyclin E1 (r = −0.783, P = 0.002)." (PMID 23383003, 2013). "To further investigate the role of Cyclin D1 and Cyclin E1 repression in miR-195-induced glioma cell growth arrest, we first examined the effects of Cyclin D1 and Cyclin E1 re-introduction on glioma cell proliferation." (PMID 23383003, 2013). "We demonstrated that miR-195 promotes glioma cell proliferation by directly targeting the 3′-UTRs of cyclin D1 and cyclin E1, consequently reducing phosphorylation of pRb and downregulating the proliferative marker PCNA." (PMID 23383003, 2013). "Together, these findings suggest that NOTCH3 is highly likely to induce glioma cell invasion and proliferation via at least the activation of CCND1, cMYC and EGFR gene expression." (PMID 24143218, 2013). "Taken together, these results suggest that both Cyclin D1 and Cyclin E1 downregulations contribute to miR-195-induced glioma cell growth arrest." (PMID 23383003, 2013). "Inhibition of PHGDH expression in glioma cells downregulated the expression of VEGF, MMP-2, CHK2 and cyclin D1 and reduced glioma cell proliferation, invasion and tumorigenicity in vitro and in vivo." (PMID 23229761, 2013). "Taken together, our results suggest that miR-195 plays an important role to inhibit the proliferation of glioma cells, and present a novel mechanism for direct miRNA-mediated suppression of cyclin D1 and cyclin E1 in glioma." (PMID 23383003, 2013). "This modulatory effect of NOTCH3 can be predominantly attributed to NOTCH target genes as well as its potential cooperation with major aberrant signaling pathways in malignant glioma such as EGFR, C-MYC and CCND1, which are all often altered in glioma." (PMID 24143218, 2013). "In accordance, cholera toxin, a potent inducer of cellular accumulation of cAMP and thereby phosphorylation of CREB, is able to cause G1 arrest by upregulation of p27, p21 and downregulation of cyclin D1 in rat and primary human glioma cells." (PMID 22404972, 2012). "Recent reports indicate that, increasedexpression of cyclin D1 leads to uncontrolled cell cycle in glioma biopsies; breast,head, neck, esophageal, rectal carcinomas; and astrocytoma cell lines." (PMID 21455311, 2011). "In good correlation with our data, lower expression of E2F1, a target of miR-20a and cyclin D1, a target of both miR-20a and miR-17 was found to predict longer survival in gliomas." (PMID 21483847, 2011). "Cyclin D1 overexpression, CDKN2A loss, and pRb inactivation play a key role in glioma tumorigenesis." (PMID 21843312, 2011). "Our immuno precipitation experimentspresent evidence that, treatment of glioma cells with hUCBSC leads to thearrest of cell-cycle progression through inactivation of both cyclin D1/Cdk4 and cyclin D1/Cdk 6 complexes." (PMID 21455311, 2011). "Here we show that a lower expression of CDKN2A and a higher expression of cyclin D1 in the patients with high-grade malignant gliomas than low-grade gliomas, respectively." (PMID 21843312, 2011). "hUCBSC when co-cultured with glioma cellsdepicts both fascaplysin and thymidine activity in part, by showing reducedG0-G1 phase, reduced cyclin D1 and Cdk 4 expressionlevels, and increased G0-G1 phases with decrease in thecyclin D1 and Cdk 4 expression levels." (PMID 21455311, 2011). "In another experiment, wesynchronized the glioma cells in G0-G1 phase using 4 mMthymidine for 12 h in order to study the expression of cyclin D1 and Cdk 4 inthe G0-G1 phase." (PMID 21455311, 2011). "It isplausible that hUCBSC reduced cyclin D1 expression in glioma cells within theircontact and in the surrounding areas." (PMID 21455311, 2011).
glioma (continued). "An increase in p21 and p27, and decrease in cyclin D1 and cMyc levels was observed in glioma cells upon Iripallidal treatment." (PMID 20576128, 2010). "All three high grade lines had highly complex genomic profiles and harboured amplifications and deletions at several known cancer genes dysregulated in paediatric glioma, including CCND1, MYC, CDK4, PIK3CA, CDKN2A/B, and RB1." (PMID 19365568, 2009). "Dlk1 expression is increased in gliomas and over-expression in transfected cells promotes cell proliferation by inducing the expression of cyclin D1, CDK2, and E2F4." (PMID 19331679, 2009). "Similarly, BTG1 contributes to the growth arrest of glioma cells through the regulation of cyclin D1 and p21 expression." (PMID 42080092, 2026). "Similarly, the increase in cyclin D1 due to miR-15b downregulation can improve cell proliferation, while cyclin D1 knockdown inhibits the proliferation and invasion of glioma cells by inducing apoptosis." (PMID 37509289, 2023). "However, the detailed mechanisms by which BTBD10 downregulates cyclin D1 and p-Akt in glioma cells will require further investigation." (PMID 36045715, 2022). "Additionally, small nucleolar RNA host gene 16 (SNHG16) suppressed the expression of p21, caspase-3 and caspase-9, while promoting cyclin-D1 and cyclin-B1 expression to inhibit apoptosis in glioma cells." (PMID 35601497, 2022). "However, aberrant gene amplification and overexpression of cyclin D1 have been observed in glioma biopsy specimens and a small number of malignant glioma cell lines." (PMID 35223330, 2022). "Our prior data discovered that TNKS1 could facilitate the β-catenin nuclear transport, which further activates downstream target gene transcription expression, including Cyclin D1 and c-myc, to stimulate glioma cell proliferation and invasion." (PMID 35450028, 2022). "Thus, the anti-tumorigenic effects of BTBD10 overexpression in glioma cells were likely mediated, at least in part, by cyclin D1- and Akt-dependent signaling pathways." (PMID 36045715, 2022). "A recent study reported that cyclin D1 is a direct target of miR-195 in glioma." (PMID 35287551, 2022). "On the other hand, considering the significant regulation of cell phenotypes by CDC42EP3 knockdown, it was demonstrated that the regulatory effects of CDC42EP3 knockdown on glioma failed on condition of CCND1 overexpression, indicative of the key role played by CCND1 in downstream of CDC42EP3." (PMID 35365622, 2022). "Finally, HuR interacts with circCCNB1 and miR-516b-5p and cooperates to stabilize cyclin-D1 (CCND1) mRNA in glioma, thereby favoring cancer progression." (PMID 35884580, 2022). "Flow cytometry data showed that the knockdown of SIPA1 in A172 cells arrested cell cycle progression in the G1 phase, which was further supported by the downregulation of cell cycle proteins Cyclin A2, Cyclin D1 and Cyclin E1 in glioma cells with SIPA1 knockdown." (PMID 35431649, 2022). "As a result, our findings indicated that CDC42EP3 may be a tumor-promoting factor in glioma progression via mediating CCND1." (PMID 35365622, 2022). "NF‐κB regulates cyclin D1 and cyclin E1 expression to regulate glioma cell growth and invasion." (PMID 35945910, 2022). "AKT1, MTOR, CCND1, and EGFR are closely associated with autophagy and apoptosis in glioma." (PMID 35140796, 2022). "Moreover, data analysis of TCGA indicated that CCND1 also showed upregulated expression in glioma in comparison with normal brain tissues with an AUC of 0.909." (PMID 35365622, 2022). "Taken together, these results demonstrated that HDGF-mediated c-Jun regulation could promote glioma cell proliferation by inducing CCND1/CDK4/CDK6." (PMID 34959221, 2021). "Indeed, these two KEGG pathways share many genes, such as CCND1, which plays a fundamental role in the regulation of cell cycle and proliferation in both glioma and PCa cells and whose deregulation portends worse clinical outcomes." (PMID 34828332, 2021).
glioma (continued). "Collectively, these results revealed that RAP1B and CCND1 could activate the PI3K/AKT/mTOR signaling pathway in glioma cells." (PMID 33676540, 2021). "Besides, NE promotes the proliferation of glioma cells by regulating the expression of cyclin D1/CDK4/6 and Bcl‐2/Bcl‐XL, while curcumin can reverse these effects to alleviate tumour progression induced by adverse psychological stress." (PMID 34169637, 2021). "By performing cellular and animal experiments, we confirmed that the transcription factor E2P1 can induce transcriptional repression of miR‐107 and block its inhibitory effect on CCND1, which leads to the malignant development of glioma with the involvement of the Wnt/β‐catenin signaling pathway." (PMID 34758200, 2021). "In addition, compared to NC mimic, transfection of miR‐107 mimic significantly reduced the CCND1 expression in the glioma cells." (PMID 34758200, 2021). "In addition, guanine supplementation partially rescued IDHmut glioma cell growth, mTOR signaling, and Cyclin D1 protein expression in vitro." (PMID 33681764, 2021). "Here, this study reports that there might be an E2F1/miR‐107/CCND1 axis that mediates the malignant development of glioma cells in vitro and in vivo with the implication of Wnt/β‐catenin signaling." (PMID 34758200, 2021). "We surmised that miR‐107 possibly regulates CCND1 expression to mediate glioma progression." (PMID 34758200, 2021). "ANXA2 also regulates glioma cell proliferation via the STAT3‐cyclin D1 pathway." (PMID 34047479, 2021). "Taken together, these results demonstrated that c-Jun enhanced upon HDGF overexpression could promote glioma cell proliferation by inducing the activation of the CCND1/CDK4/CDK6 signaling axis." (PMID 34959221, 2021). "Importantly, upregulation of CCND1 restored the proliferation, resistance to death, migration, and invasion of glioma cells and augmented the malignant growth of xenograft tumors." (PMID 34758200, 2021). "Furthermore, YAP overexpression was shown to increase pGSK-3-β and β-catenin, thereby upregulating cyclin D1 expression in glioma." (PMID 32366234, 2020). "In addition, CEBPB is highly expressed in glioblastoma stem cells and has been shown to promote glioma progression by regulating cyclin D1 and inducing distinct resistance to chemotherapy." (PMID 32084215, 2020). "Additionally, the Wnt target genes C-myc and cyclin D1 were also negatively correlated with Presenilin1 mRNA levels in glioma patients." (PMID 32046730, 2020). "UCA1 could promote the proliferation and cell cycle of glioma cells via the up-regulating of cyclin D1 transcription." (PMID 31798345, 2019). "The mechanism of GATAD1 amplification promoting glioma cell proliferation was mediated by CCND1." (PMID 31286678, 2019). "This study revealed that as the grade of astrocytic tumors increases, the expression level of cyclin D1 increases as well, suggesting that cyclin D1 can promote the development of glioma and, therefore, can be used as an indicator in the judgment of the prognosis of glioma." (PMID 31583003, 2019). "In this study, we found that GATAD1 could directly target the CCND1 gene, promoting CCND1 transcription and accelerating glioma cell G1–S cycle transition." (PMID 31286678, 2019). "In addition, we revealed that decreased miR-17 in glioma cells correlated with increased expression of Cyclin D1." (PMID 29351283, 2018). "Therefore, we aimed to explore effects of miR-17 mimics or inhibitor on the viability and migration of rat glioma C6 cells, and investigate possible mechanisms by examining protein expression of cyclin D1, p-Akt and Akt in current study." (PMID 29351283, 2018). "Moreover, we found that miR-29s-induced TRAF4 knockdown markedly blocked the phosphorylation of AKT and GSK-3β as well as the expression of cyclin D1 and c-Myc in glioma cells." (PMID 30348972, 2018).
glioma (continued). "Therefore, it is possible that MiR-17 also targets the 3' UTR of Cyclin D1 gene in glioma cells, and decreased the protein expression of Cyclin D1 as shown in current study." (PMID 29351283, 2018). "Cyclin D1 overexpression has been shown to correlate with early cancer onset and with tumor progression and has been observed in a large variety of tumors including gliomas." (PMID 29489901, 2018). "In addition, protein expression of Cyclin D1, p-Akt and Akt in MiR-17 mimics or inhibitor-transfected glioma C6 cells was detected by Western Blot." (PMID 29351283, 2018). "We also found a significant two-locus model (p=0.0010) involving rs603965 within CCND1 gene and rs1346787 within EFEMP1 gene, participants with rs603965 - GA or AA and rs1346787- AG or GG genotype have the highest glioma risk, compared to participants with rs603965 - GG and rs1346787- AA genotype." (PMID 28380465, 2017). "Recent years, the genetic factors including single nucleotide polymorphisms (SNPs) may also exert effects on the development of glioma, including Cyclin D1 (CCND1) and EFEMP1 gene." (PMID 28380465, 2017). "Another study reported that inhibiting the expression of Pygo2 could decrease the proliferation, colony formation, and BrdU incorporation of gliomas by reducing cyclin D1, a downstream gene of the Wnt/β-catenin signaling pathway." (PMID 28837560, 2017). "Since CCND1 is one of the molecules which regulate the process from the G1 phase into the S phase, we hypothesized that CCND1 may be regulated by EGR1 in glioma." (PMID 29246166, 2017). "Furthermore, ibrutinib treatment increases the expression levels of the cell cycle inhibitory proteins p21 and p27, and decreases the levels of Cyclin D1 in glioma cells." (PMID 28946903, 2017). "We found a significant two-locus model (p=0.0010) involving rs603965 within CCND1 gene and rs1346787 within EFEMP1 gene, participants with rs603965 - GA or AA and rs1346787- AG or GG genotype have the highest glioma risk, compared to participants with rs603965 - GG and rs1346787- AA genotype." (PMID 28380465, 2017). "To identify the molecular mechanisms by which netrin-1 promoted cell proliferation and glioma growth, we examined the expression levels of several key molecules related to cell proliferation and the cell cycle, including c-Myc, cyclin D1, p27, cyclin E and cdk2 in U251 and U87MG cells." (PMID 28710382, 2017). "Moreover, the combination of differentiation-inducible drugs and inhibition of cyclin D1 feedback can enhance the differentiation efficiency of glioma cells." (PMID 27515956, 2016). "The results suggest that interventions inhibiting cyclin D1 feedback could help to enhance drug-induced differentiation efficiency in a noisy environment during glioma differentiation therapy." (PMID 27515956, 2016). "Our stochastic simulation demonstrated that noise not only renders some glioma cells insensitive to cyclin D1 degradation during drug treatment but also induce heterogeneous differentiation responses among individual glioma cells by modulating the ultrasensitive response of cyclin D1." (PMID 27515956, 2016). "In this study, we revealed that cyclin D1 ultrasensitivity might result in qualitative modification of the probability distribution of glioma cell differentiation due to the stochastic noise in molecular processes." (PMID 27515956, 2016). "Furthermore, we demonstrated by qRT-PCR that the transplanted glioma cells highly expressed Nos2, Vegfa and Cyclin D1 mRNA." (PMID 25768009, 2015). "Glioma and zebrafish derived Vegfa and tumor Cyclin D1 expression could be down regulated by the nitric oxide scavenger 2-(4-Carboxyphenyl)-4,4,5,5-tetramethylimidazoline-1-oxyl-3-oxide or CPTIO." (PMID 25768009, 2015).